IL2 (interleukin 2)
Diseases named in the same sentence as IL2 in open-access papers (continued):
Sharing a sentence is not in itself a finding about the gene and the disease.
infection (continued). "Prior to infection, we verified that CCL19-treated CD4 + T cells exhibited minimal expression of CD69 and CD25, confirming a resting phenotype, whereas cells treated with phytohaemagglutinin (PHA) and interleukin-2 (IL-2) for 24 hours showed robust upregulation of both markers." (PMID 40372991, 2025). "The percentage of triple positive polyfunctional CD4+ T cells towards parental spike was slightly higher among patients with prior infection, whereas non-infected patients had slightly higher levels of TNFα+IL-2+ dual positive CD4+ T cells towards spike from BA.4/5." (PMID 38326340, 2024). "Finally, after infection, the secretion of IFN-γ and IL-2 cytokines showed a discreet decrease trend after infection in some subjects, but this result is not statistically significant." (PMID 38812507, 2024). "Finally, based on the ROC curve analysis, we suggest that IL-2 may be a potential biomarker of DENV infection and that IFN-α and IFN-γ may be potential markers for primary versus secondary infection in DENV-infected patients." (PMID 38003826, 2023). "The IL-2-producing T cells targeting nucleoprotein and an in silico designed pool of epitopes conserved across HCoV were significantly enriched in household contacts that did not have a detectable infection relative to those who seroconverted." (PMID 36901802, 2023). "In addition, some studies found that the levels of IL‐2, IL‐4, IL‐6, IL‐7, IL‐10, IP‐10, MCP‐1, TNF‐α, MIP‐1α, IFN‐γ, and G‐CSF in patients with severe COVID‐19 infection were significantly higher than those in patients with mild and moderate infection." (PMID 36684101, 2023). "Others, such as IL-1α, IL-2, IL-7, IL-9, IL-10, IL-12p40, IL-13, and VEGF were present at equivalent concentrations in lungs of infected and control mice during the first 5 days, but at significantly reduced concentrations in lungs of infected mice at day 7 post-infection." (PMID 35812400, 2022). "It was reported that mice treated with IL-2 blocking monoclonal antibodies could not resist the infection of L. donovani, while the infected mice receiving exogenous IL-2 had reduced parasite loads, relative with controls." (PMID 35812381, 2022). "At the early time point of infection, the reduced percentage of CD25+ cells correlated with suppressed overall expression of the high-affinity IL-2Rα (CD25) on the entire population Further, we found that in vitro-stimulated cells from Adrb2-ko mice secreted significantly less IL-2 than WT cells." (PMID 35944008, 2022). "Regardless of CLR treatment, CFA+GLA-SE/CDG immunization significantly elicited Mav CFA-specific CD4+CD44+CD62 L− T cells producing IFN-γ+IL-17A+, and IFN-γ+TNF-α+ but not IFN-γ+IL-2+ in the lungs in the CFA+GLA-SE/CDG-immunized group compared with those in the infection control group." (PMID 35499090, 2022). "Similar to their inbred counterparts, outbred SPexp mice had increased proinflammatory cytokines (IL-2, IL-6, TNF-α, and IFN-γ), decreased cellularity in the blood, and an increased frequency of Ag-experienced CD4 and CD8 T cells within PBL 5 d after last infection, as seen in inbred SPexp mice." (PMID 35878936, 2022). "In our study, we observed that treatment with BCP-DHA, regardless of the presence of infection, negatively regulated the gene expression of IL-2, IL-6, IRF7, NLRP3, and TYK2, acting directly in NF-ĸB inhibition and the synthesis and activity of pro-inflammatory cytokines." (PMID 36357780, 2022). "For those plasma cytokines and chemokines with no sex-specific differences over the course of infection, a majority, including IL-2, IL-10, IFN-γ, MIP-1α, IL-3, IL-4, IL-5, IL-12p70, IL-13, IL-17, and G-CSF, exhibited differing temporal patterns between genotypes." (PMID 35970557, 2022).
infection (continued). "In contrast, increased levels of T cell-derived IL-2 IL-2, IL-7, IL-4, and IL-5, myeloid-derived IL-1α and 1β, and growth factors such as PDGF and TGF-α in younger individuals suggest that they develop more robust T cell responses in an attempt to clear the infection." (PMID 35401519, 2022). "This difference, observed in the current study, may be due to the type of patient samples used (serum vs nasal swabs) and suggest that the downregulation of the key cytokines, IL-2, IL-6, TNF-α, and IFN-γ, occurs in the nasopharyngeal milieu during the early infection." (PMID 36584119, 2022). "We then sought to determine whether adjunctive ZOL/IL-2 administrations, while expanding anti-TB Vγ2Vδ2 T effector cells and facilitating immune responses of CD4+ Th1 or CD8+ T effectors, led to immune resistance to MDR-Mtb V791 infection." (PMID 35765887, 2022). "Interleukin-2 (IL-2) and Interferon (IFN-γ) CD4+ and CD8+ T cell responses specific to SARS-CoV-2 spike (S), nucleocapsid (N) and membrane (M) peptides are detected in PCR-positive individuals up to 12 months after infection, including in those who are seronegative." (PMID 35772216, 2022). "Since the increase in total infection in IL-15-stimulated cells was more pronounced with R5 HIV-GKO than X4/R5 HIV-GKO, we hypothesized that IL-15 might enhance the expression of CCR5 compared to IL-2." (PMID 35499323, 2022). "The reduced production of IL-2 from SARS-CoV-2-specific CD8 T cells in HIV-infected donors could, however, hinder their proliferative potential and long-term immune memory post natural infection and/or immunization." (PMID 34611163, 2021). "In the hyperinflammatory phase, patients with severe COVID-19 exhibit higher levels of IL-2, IL-6, IL-7, IL-10, IP-10, MCP1, TNF-α, macrophage inflammatory protein 1 alpha (MIP1A), and granulocyte-colony stimulating factor (G-CSF) than patients with moderate infections (early inflammatory phase)." (PMID 34220861, 2021). "IL-2, IL-6 and TNF-α were all induced to significantly lesser extents in the cortexes of the infected TLR4mut mice compared with the infected TLR4WT mice at day 4 PI, but they were induced to similar levels in the brains of both genotypes by VEEV TC-83 infection at days 2, 6 and 8 PI." (PMID 33487119, 2021). "As expected, the expression of GATA-3 and T-bet was increased in T cells cultured with IL-2-IL-4 and IL-2-IL-12p70, and IL-2-IL-12-cultured T cells, but not IL-2-IL-4-cultured T cells, significantly inhibited Mtb growth in macrophages compared to the infection control." (PMID 34299161, 2021). "While several other studies have shown the capacity of IL-2 to limit TFH differentiation in adult mice, here, we show for the first time that TFH differentiation during early-life infection is found to be exquisitely suppressed by IL-2, with virtually no TFH found in its presence." (PMID 34665220, 2021). "Type-I T cells produced type-I cytokines, such as IL-2, TNF-α, and IFN-γ, to enhance cellular response to remove infected cells, whereas Type-II T cells produced type II cytokines, such as IL-4, IL-5, and IL-10, to increase antibodies to attack exogenous antigen to prevent host-cell infection." (PMID 34200327, 2021). "In our study we did not observe an increased frequency of Tregs after clinical infection in older adults compared to youngsters, not favouring of a major role for Tregs in IL-2 consumption or reduced CD4+ memory T-cell proliferation in older adults in our study." (PMID 35822011, 2021). "No serious infection occurred in the IL-2 group, but two in placebo group." (PMID 33868284, 2021). "Importantly, much more of IFN-γ+ or IL-2+ T cells, IFN-γ+ TEM cells and IL-2+ TCM cells were induced in the spleen and the lung DMT-adjuvanted CMFO subunit-vaccinated mice than the CMFO/MTO group, whatever before and after infection." (PMID 32953889, 2020).
infection (continued). "Additionally, it has been reported that HIV-specific CD4 T-cell responses (IFN-γ, IL-2, TNF-α) during early infection or untreated infection may predict disease progression and effective viral control." (PMID 32941433, 2020). "The ESAT-6-specific IL-17-, IFN-γ-, TNF-α-, and IL-2-producing CD4+ T-cell population in the lungs and spleen was considerably larger than that in BCG-immunised and BCG-primed ESAT-6-boosted mice, and Ag-specific CD4+CD44+ T-cells in the lungs were expanded when compared to pre-infection numbers." (PMID 32545304, 2020). "Third, both the Dual-reporter and Wild-type models activate the cells prior to infection and/or culture the cells in the presence of IL-2, and these activation-induced changes might not have resolved by the time the cells were analyzed." (PMID 33253324, 2020). "Protection against active TB is known to require a clearly delineated T-helper type 1 (Th1) response, mediated by interferon-gamma (IFNγ), interleukin-2 (IL2), and tumor necrosis factor-alpha (TNFα), which may clear infection or drive it into an immune-mediated containment or latency." (PMID 32498074, 2020). "Moreover, microarray assay in combination with CRNG interference and overexpression showed that the differential genes such as ANPEP, KITLG, STAT5A, FOXP3, miR-451, IL-2, IL-10, IL-6, and TNF-α are mainly involved in viral and pathogens infection and the immune-inflammatory responses in PK-15 cells." (PMID 31178726, 2019). "However local inflammation during biofilm infection was also characterized by increased abundance of IL-2, which was not significantly elevated in our infection model." (PMID 30978245, 2019). "Likewise, the chimera promoted the strongest CD8+ T cell response after infection, but shared its predominance with the F3 vaccine, for the frequencies of single producers of IL-2 and double producers of TNF-α and IL-2, and TNF-α and IFN-γ and multifunctional CD8 T cells." (PMID 31024556, 2019). "Analysis of CD4+ T cell subsets revealed an increase in TFH cells and IFNγ-, IFNγ+ TNF+-, and IL-2-producing CD4+ T cells and a decrease in Treg cells in Mock-immune compared with ZIKV-immune mice, which is consistent with the observation that Treg cell number peaks at day 3 after primary infection." (PMID 30677097, 2019). "IL-2 mRNA expression was dimorphic only in sham-infected animals and was not affected by infection." (PMID 30515051, 2018). "In addition, immune responses were studied based on titer levels of the virus antibody and the levels of inflammatory cytokines interleukin (IL)-2 and interferon (IFN)-γ, and most levels were significantly upregulated, indicating that the host immune responses were activated early in infection." (PMID 30510548, 2018). "Severe IV infection induces many cytokines; IFNαβ, TNFα, IFNγ, C-X-C motif chemokine (CXCL) 10 (CXCL10), CXCL9, C-C motif ligand (CCL) 2 (CCL2), CCL4, CCL5 and interleukin (IL)−6 (IL-6), IL-2, IL-8, and IL-10 have all be observed to be upregulated during severe IV infection in humans." (PMID 30250466, 2018). "Twenty-four hours after infection, we assessed inflammatory responses of the macrophages by measuring the levels of cytokines, including granulocyte/macrophage colony-stimulating factor (GM-CSF), IFN-γ, interleukin (IL)-2, IL-4, IL-6, IL-8, IL-10 and TNF-α, secreted in the culture supernatant." (PMID 29712918, 2018). "Type I cytokines such as IL-2, IFN-γ, and TNF-α increased gradually in the sera of both the RH and ME49 groups, and there was an earlier significant increase of IFN-γ at day 3 post-infection in the RH group (RH group vs. Control group: 12.74 ± 1.15 vs. 4.33 ± 0.88, P < 0.05)." (PMID 30564216, 2018). "The results showed that the expressions of TNF-α, IL-12, IL-5, IL-10 and GM-CSF in serum increased from five weeks post-infection and to peak levels at week 6 post-infection; however, as typical type 1 cytokines, the levels of IL-2 and IFN-γ in serum did not change during the key period." (PMID 28539607, 2017).
infection (continued). "Additionally, the IDR (p < 0.0001, R = −0.7815) and the frequencies of multifunctional CD4+ (p < 0.0500, R = −0.2803) and CD8+ T cells (p < 0.0001, R = −0.7837) expressing IL-2, TNF-α, and IFN-γ, after infection, were strong correlates of prophylactic efficacy." (PMID 28280494, 2017). "The results indicate that the expression levels of IFN-γ and IL-2, but not IL-6 and IL-4, were elevated in the Tris-HCl control or adjuvant vaccinated mouse splenocytes and had the potential for proliferation after infection of Babesia parasites or BMSA stimulation." (PMID 29312230, 2017). "Expression of the Th1 cytokine IL-2 was significantly downregulated at the first 3 days of infection, when it could not be detected at all." (PMID 29163382, 2017). "Pretreatment of the infected rat models with doses of the traditional energy tonic (100 and 20 mg/mL/kg body weight) before infection nonsignificantly increased cytokines secretion (IL-1β, IL-2, IL-10, IL-13, IFN-γ, and RANTES), while others did not change when compared to those with infection only." (PMID 28408939, 2017). "In addition, we showed that high expression of CTLA-4 and low levels of IL-2 prevented mTOR activation and Otub-1 protein expression, and maintained GRAIL expression, which inhibited T cell proliferation during the acute phase of the infection." (PMID 28114324, 2017). "Thus, overall, the addition of IL-2 and IL-6 to murine memory CD8+ T cells can boost their GrB expression, which could aid in viral clearance during an infection." (PMID 27322555, 2016). "Thus, the IL-2 elevation during acute infection is not sufficient to block the massive depletion of CD4 T cells caused by the strong cytotoxic effects of the innate immune response and the substantial cytotoxicity due to peak viremia." (PMID 27145859, 2016). "Levels of IL-2, IL-4, IL-5 and IL-13 were unaltered by infection in the presence or absence of Mtb." (PMID 26894562, 2016). "Th1 cytokines such as interleukin-2 (IL-2), interferon-γ (IFN-γ), and Tumour Necrosis Factor alpha (TNF-α) are the primary source for proinflammatory Th1 responses, in which they are effective in controlling infection with intracellular pathogens and for perpetuating autoimmune responses." (PMID 26903715, 2016). "Conversely, 15 days after treatment of blood stage infection with chloroquine, splenocytes showed spontaneous in vitro expression of TNFα, IL2, IL6, IL10, and IL12, but not IFNγ, and stimulation with P. falciparum pRBC blocked the expression of all these cytokines." (PMID 25890318, 2015). "Preliminary data suggest that exceptionally high responses to IL-2 added from the beginning may be a characteristic of particular donors rather than being due to an acute infection." (PMID 25239080, 2014). "Thus, enhanced IL-2, IL-12, TNF-α and IFN-γ mRNA expression but downregulation of IL-10, most remarkable in cocktail vaccinated hamsters is chiefly responsible for strong Th1 biased immunity after infection." (PMID 25144181, 2014). "The splenocytes of vaccinated hamsters receiving liposomal rCPC and cocktail of three liposomal CPs showed higher IFN-γ, IL-2, TNF-α and IL-12 mRNA expression than all other groups but appreciable downregulation of macrophage deactivating cytokines like IL-4, IL-10 mRNAs, before and after infection." (PMID 25144181, 2014). "Additionally, we show that neutrophil control of IL-2 mediated expansion of TH1 cells is independent of infection." (PMID 23754944, 2013). "Furthermore, uninfected mice treated with G-CSF demonstrated dampened responses to IL-2 and IL-6, indicating that neutrophil-mediated control of IL-2 induced pSTAT5 and IL-6 induced pSTAT1 responses are independent of infection." (PMID 23754944, 2013). "However, in the HIV-negative control group, the IL-2 level was not markedly different if an infection with Cryptosporidium spp." (PMID 23971713, 2013).
infection (continued). "Of the 14 Th1 response genes tested, the expression levels of 8 genes (IL2, IFNG, CSF2, TLR4, CD4, IRF1, SOCS5 and STAT4) were significantly elevated at 2 weeks and several of these (IL2, IFNG, TLR4, CD4 and STAT4) had similar expression levels at 4 and 8 weeks post-infection." (PMID 23448601, 2013). "Interestingly, TNF-α/IL-2 expressing central memory-like CD4 T cells showed a significant positive correlation with protection at week 6 post infection, whereas the opposite was observed for post infection CD4 T cells producing only IFN-γ." (PMID 23977248, 2013). "Thus, the vaccine-induced response generated by TB10.4 was very similar to the ESAT-6 induced response both in terms of magnitude and quality i.e. the proportion of IFN-γ+IL-2+TNF-α+ CD4 T cells and differed markedly from the infection promoted response to these antigens." (PMID 24349004, 2013). "An important implication of our finding is that IL-2-producing dendritic cells may control Treg fitness in vivo even in the absence of infection or other danger signals." (PMID 22984435, 2012). "Therefore, we next ascertained the cytotoxic potential and the ability of PD-1high and PD-1medium CD8 T cells to produce pro-inflammatory cytokines like IL-2, IFN-γ and TNF-α when stimulated in vitro with immunodominant SSIEFARL peptide on day six post-infection." (PMID 22808056, 2012). "Other cytokines were unchanged after infection (IL-2, IFN-γ, IL-5 and IL-13; data not shown)." (PMID 22024399, 2011). "Furthermore, prior to the onset of infection we observed changes in IL-2 and IL-7 gene expression without any change in expression of the Bcl-2 related genes." (PMID 21711552, 2011). "Intriguingly, using a T cell based neutralization assay based on MBM cells (an IL2-dependent cell line similar to MYA-1 cells), the sera from the immunized cats were found to enhance FIV infection, an effect that could be adsorbed by pre-incubation with lipo-P59." (PMID 22069520, 2011). "Following infection with the Ts strain (cell-adapted virus) these cytokine transcripts were up-regulated at 5 days post-infection (dpi), 2- and 13-fold respectively (P < 0.05), while the expression levels of IL-2 and IL-4 were not significantly different (P > 0.05)." (PMID 21143846, 2010). "Monofunctional IL-2 or TNF-α producing HIV-specific CD8+ T cells were very infrequent in this cohort of chronically infected patients and only a small proportion of HIV-specific CD8+ T cells expressed TNF-α responses confirming previous studies that this effector function is lost early in infection." (PMID 20638093, 2010). "At 48 hours after infection, the infected cells were cultured without IL-2 in a 96 well plate." (PMID 17140451, 2006). "However, IFN-γ, IL-2, and TNF-α levels and vaccine-specific antibody concentrations in the plasma were significantly elevated in the rEg.P29T+B + CpG + infection and rEg.P29 + CpG + infection groups compared to those in the PBS + infection and CpG + infection groups." (PMID 40266142, 2025). "However, according to our correlation analysis, it can be assumed that after mpox infection, the CD8+ T cells may contribute to a greater extent to the IFN-γ and IL-2 ELISpot response because CD8+ T cells showed significant positive correlation with ELISpot responses in contrast to CD4+ T cells." (PMID 38400115, 2024). "In vitro IL-2, IFNγ and IP-10 responses to C. burnetii were significantly elevated in exposed compared to unexposed participants, regardless of whether exposure occurred through infection or vaccination." (PMID 35812430, 2022). "Given the diminished nature of IL‐2 production in SARS‐CoV‐2‐specific TH1‐type cells amongst asymptomatic donors, IFN‐γ is a more reliable read‐out when assessing for the presence of T‐cell responsiveness in participants with unknown infection history or vaccination status." (PMID 34775604, 2022).